IL1B (interleukin 1 beta)
Diseases named in the same sentence as IL1B in open-access papers (continued):
Sharing a sentence is not in itself a finding about the gene and the disease.
generalized epilepsy (3 papers, 2021 to 2025). Epilepsy that is characterized by generalized seizure types and may have typical interictal and/or ictal EEG findings that accompany generalized seizure types (for example generalized spike-wave). "Baseline gene expression analysis in patients with generalized epilepsy revealed significant activation of gene pathways suggestive of systemic immune activation, such as Rap1 signaling, an upstream regulator of IL-1β production by the NLRP3 inflammasome." (PMID 34208064, 2021). "The aim of this study was the investigation of TNF-α, IL-10, IL-6, and IL-1β cytokines secretion in PBMC supernatants isolated from children affected by generalized epilepsy and treated in vitro with myofibrillar, sarcoplasmic, and total protein fractions of meat and fish sources." (PMID 35684043, 2022). "A clinical study of 21 generalized epilepsy patients revealed that VPA treatment for 4–6 months decreased the serum level of IL-6 but not that of IL-1β or TNF-α." (PMID 40806813, 2025).
Giardia infection (3 papers, 2019 to 2022). "In the present study, we confirmed the involvement of A20-mediated NLRP3 deubiquitination in inflammasome activation, CASP1 and GSDMD cleavage, and IL-1β and IL-18 release during Giardia infection." (PMID 34943932, 2021).
gingival enlargement (3 papers, 2020 to 2025). "The authors considered IL-1β a risk factor for the development of gingival enlargement." (PMID 32064567, 2020).
goiter (3 papers, 2015 to 2025). Enlargement of the thyroid gland usually caused by lack of iodine in the diet, hyperthyroidism, or thyroid nodules. "qRT-PCR analysis revealed a higher expression of IL-1β in thyroid glands from both GD and TH compared to goiters (p<0.05 in both cases)." (PMID 25880730, 2015). "On the other hand, IL-1β was able to induce the production of hyaluronan by thyroid epithelial cells and thyroid fibroblasts, a process possibly contributing to the progression of goiter in GD." (PMID 34033291, 2021).
hantavirus infection (3 papers, 2014 to 2024). "STING agonist treatment or STING overexpression significantly upregulated IFNs, pro-inflammatory cytokines (IL-1β), and interferon-stimulated genes (ISGs) (for example, Mx1 and ISG56) upon hantavirus infection." (PMID 38932148, 2024).
histoplasmosis (3 papers, 2017 to 2025). A disease caused by the fungus Histoplasma capsulatum. "Significant differences in the median values of IL-1β, TNF-α, IFN-γ, IL-18, IL-17A, IL-33, IL-13, and CXCL8 were reached in all the groups studied, suggesting that these cytokines play a role in the inflammatory processes associated with histoplasmosis and pneumocystosis." (PMID 34829225, 2021). "Elevated IL-1β, TNF- α, IL-18, and PTX3 levels in HIV patients with histoplasmosis could serve as a potential predictive biomarker for poor prognosis and disseminated disease development in these individuals." (PMID 40558960, 2025). "In our study, TNF-α and IL-1β together with IL-6 and IL-18 showed the highest values, with statistical differences for the group of HIV patients and Hc suggesting that these cytokines play a role in the local inflammatory processes of histoplasmosis in HIV patients." (PMID 40558960, 2025). "Significant differences in median values of SP-A, IL-1β, TNF-α, IFN-γ, IL-18, IL-17A, IL-33, IL-13, and CXCL8 were found among all the groups studied, suggesting that these cytokines play a role in the local inflammatory processes of histoplasmosis and pneumocystosis." (PMID 34829225, 2021).
Hypercalcemia (3 papers, 2018 to 2026). An abnormally increased calcium concentration in the blood. "TNF-α, IL-1β, vitamin D and PTHrP are potent calciotropic factors able to increases bone resorption and serum hypercalcemia." (PMID 29670736, 2018). "Mice administered IL-1β develop hypercalcemia and display increased osteoclast numbers, and treatment with chimeric osteoprotegerin (OPG; a RANKL antagonist) reduced hypercalcemia and osteoclast number." (PMID 35567665, 2022).
hypertrophic cardiomyopathy (3 papers, 2017 to 2024). A condition in which the myocardium is hypertrophied without an obvious cause. "Studies indicate elevated levels of cytokines like TNF-α, hs-CRP, and inflammatory interleukins (e.g., IL-1β, IL-1RA, IL-6, IL-10, circulating monocyte chemoattractant protein resulted in a chronic low-grade inflammatory state in hypertrophic cardiomyopathy (HCM)." (PMID 38533084, 2024).
Hypoalbuminemia (3 papers, 2019 to 2025). The concentration of albumin in the blood circulation is below the lower limit of normal. "A further immunological cascade boosts IL-6 and IL-1β levels, causing increased blood vessel permeability, leading to transcapillary albumin loss and hypoalbuminemia." (PMID 41008744, 2025). "IL-1β and TNF-α may also contribute to the hypoalbuminaemia and weight loss seen in FIP via decreased albumin production and increased muscle breakdown respectively." (PMID 31835559, 2019).
Hypoxemia (3 papers, 2018 to 2020). An abnormally low level of blood oxygen. "HH group showed the highest expression levels of IL‐1β in comparison with Hypoxemia group (P < .01) and Hypercapnia group (P < .01)." (PMID 32666671, 2020). "HH group had the strongest IL‐1β fluorescence as compared with Hypoxemia group and Hypercapnia group." (PMID 32666671, 2020). "Simple effects analyses found increased protein expression levels of IL‐1β in Hypoxemia group (P < .01), but not in Hypercapnia group (P > .05) compared with Sham group." (PMID 32666671, 2020). "Enhanced IL‐1β immunofluorescence was observed in Hypoxemia group, but not in Hypercapnia group compared with Sham group." (PMID 32666671, 2020).
interstitial nephritis (3 papers, 2015 to 2021). Inflammation of the renal tubules and supporting tissues of the kidney. "A significant positive correlation has been reported in the PAN model between the severity of interstitial nephritis, as determined by increased CD68 positive macrophages, MCP-1 and IL-1β, and the degree of proteinuria." (PMID 26014479, 2015).
intracranial aneurysm (3 papers, 2022 to 2025). "IL-1β is important for the progression of intracranial aneurysms and acts as a representative cytokine secreted by M1 macrophages." (PMID 37223093, 2023). "IL-1β is one of the 3 members of the IL-1 family, which was highly expressed in intracranial aneurysm samples." (PMID 35469231, 2022). "Experimental animal studies have shown that intracranial aneurysm formation, progression, and rupture could be mitigated by inhibiting SASP factors such as IL‐1β, TNF‐α, MCP‐1, and MMPs." (PMID 41026146, 2025). "Moreover, we observed the levels of IL-1β and tumor necrosis factor a (TNF-α) increase with the upregulation of FGB in human intracranial aneurysm cells." (PMID 35469231, 2022).
ischemic optic neuropathy (3 papers, 2020 to 2023). "The IL-1β level is significantly increased in the optic nerve head tissue in patients with ischemic optic neuropathy." (PMID 37180697, 2023). "However, overactivated microglia provide excessive amounts of the inflammatory ligands IL-6, IL-1β, and TNF-α, causing ROS, iNOS, NFκB, and NLRP3 inflammatory complex activation; additionally, disruption of neuronal homeostasis was observed in ischemic optic neuropathy." (PMID 34573098, 2021). "Lin and co-authors suggested that AST achieved neuroprotective effects in ischemic optic neuropathy model mice by downregulating both oxidative and inflammatory cascades, as AST administration also reduced the expression of TNFα and IL1β in retinas." (PMID 33014448, 2020).
kidney cancer (3 papers, 2017 to 2025). Primary or metastatic malignant neoplasm involving the kidney. "Here, we found that, in HEK293 kidney cancer cells, TGR5-transfected cells with the ligand treatment suppressed gene expression of IL-1α, IL-1β, IP-10, and MCP-1 induced by TNF-α or p65 overexpression." (PMID 28903349, 2017).
laryngeal squamous cell carcinoma (3 papers, 2021 to 2024). A squamous cell carcinoma that arises from the larynx. "In this study, it was also demonstrated that IL-1β-IL-6, and IL-8 are abnormally overexpressed in poorly differentiated laryngeal squamous cell carcinoma, indicating a significant difference compared to the control group." (PMID 38920620, 2024). "Meanwhile, IL-1β also plays an important role in the differentiation of laryngeal squamous cell carcinoma." (PMID 38920620, 2024).
lichen planus (3 papers, 2020 to 2025). A chronic, recurrent, pruritic inflammatory disorder of unknown etiology that affects the skin and mucus membranes. "A downregulation in lichen planus was observed, suggesting that IL-1β could have a potential pathogenic role as CARD18 is a negative regulator of inflammasome activation." (PMID 41301909, 2025). "Our findings demonstrate a statistically significant increase in the expression of IL-1β, IL-6, and RIPK3 in the skin biopsy samples of SJS/TEN patients compared to those of lichen planus (LP) patients and normal controls." (PMID 39941220, 2025). "Our findings highlight that IL-1β, IL-6, and RIPK3 play pivotal roles in these disease processes, with significantly elevated expression levels observed in the skin of SJS/TEN patients compared to those with lichen planus (LP) or normal controls." (PMID 39941220, 2025). "Our findings indicate that IL-1β, IL-6, and RIPK3 may play potential roles in the disease process, with significantly elevated expression levels in the skin of SJS/TEN patients compared to those with lichen planus (LP) or normal controls." (PMID 39941220, 2025).
liposarcoma (3 papers, 2013 to 2024). A usually painless malignant tumor that arises from adipose tissue. "Particularly, H3K9me2 has been reported as an epigenetic regulator of TNFα, IL-6, and IL-1β in the human-derived liposarcoma cell line SW872 stimulated with LPS." (PMID 39768289, 2024).
liver abscesses (3 papers, 2018 to 2025). "It promoted liver repair, inhibited amoebae presence, and modulated inflammatory cytokines (TNF-α, IL-1β, IL-10), reducing liver abscess progression to just 9.49%, compared to 84% in untreated animals." (PMID 40077770, 2025). "The results for expression levels of TNF-α, IL-6 and IL-1β in tissue at the edge of liver abscesses were similar to the immunohistochemistry data." (PMID 29420539, 2018).
lupus erythematosus (3 papers, 2017 to 2025). An autoimmune, connective tissue chronic inflammatory disorder affecting the skin, joints, kidneys, lungs, heart, and the peripheral blood cells. "In lupus erythematosus, IFNs, particularly IFN-κ and IFN-α, amplify inflammatory cascades in the skin characterized by cytokines such as IL-6, IL-1β, and TNF-α, and chemokines (CXCL9, CXCL10), resulting in sustained immune cell infiltration." (PMID 41479908, 2025).
Lymphadenopathy (3 papers, 2013 to 2025). Enlargement (swelling) of a lymph node. "A plausible hypothesis is that lymphadenopathy reflects heightened systemic inflammation and immune activation driven by excessive cytokine production (e.g., IL-1β, IL-6, IL-18)." (PMID 39797367, 2025). "Here IL-1β+ and TNF-α+ were both more frequent in patients with lymphadenopathy, and were positively correlated with granzyme expression, and necrosis was also strongly directly correlated with IL-1β+, which suggests that this cytokines plays a key role in the pathology of CL." (PMID 32766167, 2020). "Regarding the molecules secreted by these cells, IL-1β+ and TNF-α+ were found to be the most highly expressed, mainly in individuals with lymphadenopathy, followed by perforin+ and granzyme B+." (PMID 32766167, 2020). "Similarly, IL-6 (P=0.0006), IL-10 (P=0.001), IL-12p40 (P=0.03), TNFα (P≤0.002) and chemokines MIP-1β (P<0.0001) and MCP-1 (P=0.002) (but not IL-1β, IL-13 and G-CSF) were significantly elevated in Tg mice at late stages of lymphadenopathy (Tg L) relative to WT controls." (PMID 23985023, 2013).
lysosomal disorder (3 papers, 2020 to 2024). "It has been proven that autophagy controls IL-1β secretion by targeting pro- IL-1β for degradation and it has been extensively proven that there is a progressive block of autophagy in lysosomal storage disorders, including MPS." (PMID 35645812, 2022). "Given that both primary and secondary storage substrates were required to initiate NLRP3 inflammasome‐mediated IL‐1β secretion, it is likely that several other lysosomal storage diseases, accumulating similar substrates, will share a similar mechanism of neuroinflammatory activation." (PMID 32057196, 2020).
mammary adenocarcinoma (3 papers, 2020 to 2023). "In agreement with previous findings, the exposure of breast adenocarcinoma cells to 43 °C HS resulted in the attenuation of the immediate NF-κB signalling and gene expression response to TNFα and IL1β stimulation." (PMID 32448393, 2020).
melancholia (3 papers, 2018 to 2023). A subtype of depression characterized by the inability to find pleasure in positive things combined with physical agitation, insomnia, or decreased appetite. "We are not aware of any other data linking lowered IL-1α serum levels to melancholia, although increased mitogen-stimulated levels of IL-1β were found in melancholic depression." (PMID 29103192, 2018).
monoclonal gammopathy (3 papers, 2014 to 2024). A condition characterized by the abnormal presence of monoclonal immunoglobulins in the blood or urine. "Intriguingly, in CAPS, long-term excessive IL-1β signaling does not result in a monoclonal gammopathy." (PMID 25905009, 2014). "Neither several years of monotherapy with IL-1Ra, nor several months of treatment with IL-1β antibodies or an IL-1R fusion protein led to a decrease in the monoclonal gammopathy in all other patients." (PMID 25905009, 2014).
MRSA pneumonia (3 papers, 2013 to 2024). "And increased weight loss in MRSA pneumonia secondary to IAV infection was related to decreased concentration of IL‐1β in serum." (PMID 32697385, 2020). "The aggravated inflammatory pathology in MRSA pneumonia secondary to IAV infection was associated with decreased expression of IL‐1β." (PMID 32697385, 2020). "Follow-up studies are needed to determine whether decreased IL-1β levels are also associated with increased inflammation in MRSA pneumonia in humans." (PMID 39460273, 2024). "The present study supports previous findings that immunotherapy targeting the NLRP3 inflammasome or IL‐1β signaling pathway may reduce the severity and improve the clinical outcomes in MRSA pneumonia secondary to IAV infection." (PMID 32697385, 2020). "Immunotherapy targeting the IL‐1β signaling pathway could be possible therapeutic strategy for secondary MRSA pneumonia." (PMID 32697385, 2020). "MRSA pneumonia induced an increase in IL-6, G-CSF, TNFα, IL-1β, and IL-10." (PMID 24204769, 2013). "Additionally, based on murine models, it is likely that decreased IL-1β may significantly impair adaptive immune responses and promote increased inflammation in patients with MRSA pneumonia." (PMID 39460273, 2024).
mucocutaneous leishmaniasis (3 papers, 2019 to 2025). The most common form of leishmaniasis that is transmitted through the bite of female phlebotomine sand flies or after exposure to leishmania parasites. "In particular, the high densities of NLRP3+, AIM-2+, and IL-1β+ cells found in the hyperreactive form of the disease suggest a role in exacerbating the inflammatory response in patients with mucocutaneous leishmaniasis (MCL)." (PMID 40431153, 2025).
mycobacterial infection (3 papers, 2018 to 2022). "Among the molecules, chemokines (CCL3, CCL4, CCL5) and cytokines (IL6, IL1B) are known to induce M1 macrophage polarization in response to mycobacterial infection." (PMID 35821058, 2022). "The concentrations of IL-13 and IL-1β were found to be significantly reduced in hospitalised cats when compared to both control cats and those with mycobacterial infections." (PMID 30470763, 2018).
mycoplasma infection (3 papers, 2015 to 2025). "Interleukin-1β (IL-1β) is a prototypic multifunctional cytokine and can affect almost every cell type during Mycoplasma infection." (PMID 28854912, 2017).
myocardial disorder (3 papers, 2023 to 2025). A disorder that affects the muscle tissue of the heart. "Although no universally accepted definition or diagnostic criteria for septic cardiomyopathy exist, it is a reversible myocardial disorder driven by inflammatory mediators such as endotoxin, tumor necrosis factor-alpha (TNF-α), and interleukin-1-beta (IL-1β)." (PMID 39479085, 2024).
Neonatal onset (3 papers, 2018 to 2025). Onset of signs or symptoms of disease within the first 28 days of life. "Consistent with our data, a recent study identified IL-1β-producing monocytes susceptible to pyronecrotic cell death, similar to pyroptosis, in patients with Neonatal-Onset Multisystem Inflammatory Disease, the most severe form of CAPS51." (PMID 30352992, 2018).
neuritis (3 papers, 2021 to 2024). A neuropathy arising from inflammation of one or more nerves. "For example, flavanone glycosides extracted from citrus fruits can reduce the levels of IL-1β and IL-6 in patients with neuritis." (PMID 36467557, 2022). "Excessive activation of microglia is profoundly implicated in the neuroinflammation via producing a cascade of inflammatory mediators such as iNOS/NO, IL-1β, IL-6, and TNF-α, which further result in neuritis, immune response, damage of neurons, and cause cognitive dysfunction." (PMID 34485533, 2021). "The inhibitory effect of SYS18 on neuritis may be related to the protection of BBB integrity and the reduction of TNF‐α and IL‐1β in the brain." (PMID 39500736, 2024).
obstructive sleep apnea (3 papers, 2012 to 2024). "In this meta-analysis, we present the serum/plasma levels of tumor necrosis factor-alpha (TNF-α), interleukin (IL)-8, IL-1β, and interferon-gamma (IFN-γ) in both children and adults with obstructive sleep apnea (OSA) in comparison to controls." (PMID 38592305, 2024). "After the analysis of the levels of pro and anti-inflammatory markers (IL-1β, IL-4, IL-6, IL-8, IL-10, Il-15, TNF-α, CRP, α1-GP) in the tonsils, we observed higher levels of markers IL-8 and IL-10 in pediatric patients with obstructive sleep apnea syndrome." (PMID 30213594, 2020). "Patients with obstructive sleep apnea show significant increases in serum levels of TNF-α, IL-1β, and IL-6." (PMID 22578011, 2012). "Verify the levels of the inflammatory markers, IL-1β, IL-4, IL-6, IL-8, IL-10, IL-15, TNF-α, CRP and α1-GP, in the tonsils of children with and without obstructive sleep apnea syndrome." (PMID 30213594, 2020).